TNF (tumor necrosis factor)
Diseases named in the same sentence as TNF in open-access papers (continued):
Sharing a sentence is not in itself a finding about the gene and the disease.
tumor (continued). "Additionally, γδ T cells possess unique advantages, such as the ability to induce immature dendritic cells to express CD86 and MHC class I molecules via TNF-α secretion, MHC-independent antigen recognition, and direct tumor cell lysis." (PMID 41142813, 2025). "When combined with activated CTLs, it upregulated CD25 and CD69 expression on effector cells, increased the secretion of IL-2, tumor necrosis factor-α (TNF-α), and IFN-γ in vitro, and significantly curbed subcutaneous tumor growth and extended the survival time of tumor-bearing mice in vivo." (PMID 41164200, 2025). "Additionally, these vaccines stimulate the production of pro-inflammatory cytokines such as IL-12, IFN-γ, and TNF-α, which collectively support cytotoxic T lymphocyte (CTL) responses and tumour cell elimination." (PMID 40699842, 2025). "This suggests that there were variations in TNF‐α levels between the two groups on the first day after surgery, with a downward trend in TNF‐α levels observed in group E and an upward trend in group C. TNF‐α, produced by macrophages and tumor cells, has dual roles in tumor development." (PMID 40808216, 2025). "Conversely, IFN-γ and TNF-α secreted by activated Vγ9Vδ2 T cells can induce cyclooxygenase-2 (COX2) expression and prostaglandin E2 release in macrophages, which, in turn, downregulate the cytotoxic activity of γδ T cells and facilitate tumor immune evasion." (PMID 41055972, 2025). "Notably, PBMCs exposed to these supernatants exhibited an increased frequency of CD8+ T cells, accompanied by elevated IFN-γ and TNF-α and decreased TGF-β levels, consistent with a TH1-type anti-tumor immune response." (PMID 41007670, 2025). "Moreover, these GJs enable the transfer of cGAMP from tumor cells to astrocytes, inducing the secretion of inflammatory cytokines (IFN-α and TNF-α) that further fuel tumor growth and chemoresistance." (PMID 40733107, 2025). "In addition, the transcription levels of the markers of M1 macrophages, TNFα, IL12, and IL1b, were significantly upregulated after co‐culturing with PBRM1 knockdown tumor cell culture medium." (PMID 39656940, 2025). "These recruited cells secreted TNF‐α and IFN‐γ, augmenting the host anti‐tumour immune response." (PMID 39801378, 2025). "CSCs form the primary tumor can favor the diffusion of pro-tumorigenic and proangiogenic factors such as VEGF-A, TGFB1, TNF-alpha and lysyl oxidase (LOX) that induce the expression of S100A (a Ca2+ binding protein involved in endothelial remodeling) in the metastatic area." (PMID 39981232, 2025). "Recent studies indicate that the interplay of specific cytokines, including TNF and interferon-gamma (IFN-γ), might trigger PANoptosis in neoplastic cells, potentially resulting in decreased tumor size in preclinical models." (PMID 40422233, 2025). "Doenjang significantly reduced tumor formation and attenuated CAC progression by modulating inflammatory and apoptotic pathways and suppressed the expression of pro-inflammatory cytokines (TNF-α, IL-1β, and IL-6) by inhibiting the NF-κB pathway." (PMID 41154100, 2025). "Interestingly, a recent study has discovered that CD4 Th1 cells, along with myeloid cells, can exert a cytolytic effect on tumor cells via IFN-γ and TNF-α." (PMID 40564173, 2025). "Moreover, monocytes can also promote tumor growth and angiogenesis by releasing VEGF, epidermal growth factor (EGF), and tumor necrosis factor-α (TNF-α)." (PMID 40265015, 2025). "Importantly, we showed that TNF-α and TWEAK levels are elevated in the inner ear with impaired hearing on the tumor-bearing side, providing evidence that tumor-secreted TNF-α and TWEAK can reach the inner ear and potentially induce hearing loss in VS." (PMID 39923035, 2025). "Furthermore, we assessed the level of secreted cytokines, including IFN-γ, TNF-a, IL-2, and IL-10, produced from the co-culture of CAR-T cells with tumor cells at an effector-to-target (E:T) ratio of 16:1." (PMID 40722671, 2025).
tumor (continued). "Notably, STAT3 expression correlated significantly with immune modulation, particularly through suppressed NK cell activity—a key anti-tumor mechanism—potentially facilitating immune evasion via impaired IFN-γ and TNF-α production." (PMID 40636126, 2025). "Altered molecular targets, such as E-cadherin (CDH1), MMP9, Survivin (BIRC5), Cytokeratin 5 (KRT5), VEGFA, IL15, TNF-α (TNF), TRAIL (TNFSF10), and Tenascin-C (TNC), exhibited increased expression in our study, which correlates with their upregulation in tumor samples from individuals with OC." (PMID 40072102, 2025). "Moreover, El1405 intervention significantly increased the levels of TNF-α, INF-γ, and CD8 in the tumor microenvironment, while decreasing the levels of CD4, IL-6, IL-10, and TGF-β." (PMID 40568973, 2025). "Additionally, Gene Set Enrichment Analysis (GSEA) of tumor cells revealed that AB-329 induced the activation of immune and stress-related pathways (e.g., JAK/STAT3, apoptosis, TNF/NF-κB) while suppressing hypoxia and immunosuppressive signaling." (PMID 41009462, 2025). "These cells play a crucial role in tumor immunotherapy by exerting direct cytotoxicity through the production of inflammatory cytokines (e.g., interferon-gamma (IFN-γ), tumor necrosis factor-alpha (TNF-α), and interleukin-17 (IL-17)) and cytotoxic molecules (e.g., perforin and granzyme)." (PMID 40226616, 2025). "Second, our data demonstrate that GRK5 suppression substantially elevates TNF-α and IFN-γ, cytokines that induce MHC class I/II expression; this suggests GRK5 may dampen tumor immunogenicity by suppressing antigen presentation machinery." (PMID 40722845, 2025). "In tumor immunity, CD4+ Tem cells directly kill cancer cells, destroy tumor vasculature, and maintain leukocyte responses by secreting cytokines such as IFNγ and TNF." (PMID 40801655, 2025). "The immune microenvironment analysis revealed that Quetmolimab treatment significantly reduced the expression of exhaustion markers and increased the tumor reactivity of CD8+ T cells (with elevated expression of Ki67, TNF, and IFN), indicating a reduction in CD8+ T cell exhaustion." (PMID 39783838, 2025). "Further analysis revealed that tumor cells in the BI group secrete excessive IL34, which, through the IL34-CSF1R interaction, activates the ERK1/2 signaling pathway in TNF-α+ TAMs, subsequently promoting TNF-α secretion." (PMID 39865310, 2025). "M1 macrophages play a pivotal role in innate host defense and tumor cell eradication by generating reactive oxygen/nitrogen species (ROS/RNS) and pro-inflammatory cytokines such as IL-1β, IL-6, and tumor necrosis factor-α (TNF-α)." (PMID 40746825, 2025). "Once activated, γδ T cells target infected, stressed, or tumor cells using mechanisms such as cytotoxicity via perforin and granzyme secretion, antibody-dependent cellular cytotoxicity (ADCC), and the release of pro-inflammatory cytokines like TNF-α and IFN-γ." (PMID 40867289, 2025). "Collectively, these findings demonstrate that ZGE modulates multiple stress‐responsive pathways in tumor tissues, attenuating oxidative damage (via TRPM2 and SOD2), amplifying inflammatory signaling (via TNF‐α), and promoting apoptosis (via caspase‐3), particularly when combined with DOX treatment." (PMID 41306344, 2025). "These CAR-MΦ secreted elevated levels of IL-12, TNF-α, and chemokines such as CXCL9 and CCL5, which contributed to local immune activation and recruitment of CD8+ T cells and natural killer (NK) cells into the tumor bed." (PMID 40723278, 2025). "For MICA/B and PD-L1 measurement, tumor cells were co-cultured with CM from M1 macrophages, with or without anti-IL-1β, anti-IL-6, and anti-TNF-α antibodies." (PMID 40369131, 2025). "This suggests that TNF-α in cancer patients is not merely a reflection of general inflammation or nutritional status, but is more tightly connected to tumor activity." (PMID 40299527, 2025).
tumor (continued). "Additionally, immune cells within the microenvironment—particularly pro-inflammatory CD4 T cells—secrete RANKL, TNF, and TGF-β, which activate osteoclasts, enhance bone resorption, and drive tumor progression in bone, further contributing to the vicious cycle." (PMID 40149349, 2025). "TNF drives epithelial-to-mesenchymal transition (EMT), enhancing cancer cell motility and invasion, and promotes angiogenesis via VEGF induction, facilitating tumor vascularization and growth." (PMID 40547917, 2025). "Another interesting observation in our data was that TNF-α correlated preferentially with tumor-specific factors and showed only weak, non-significant correlations with systemic inflammation markers like CRP or ESR." (PMID 40299527, 2025). "In a bilateral tumor model, untreated distal tumors exhibited growth suppression when the primary tumor received “CP+-CpG + Light” therapy, accompanied by elevated IFN-γ, IL-6, and TNF-α levels in tumor tissues." (PMID 40363042, 2025). "Additionally, senescent immune system promotes chronic inflammation and angiogenesis by producing SASPs such as IL‐1, IL‐6, TNF‐α, and IFN‐γ contributing to creating a tumor‐tolerant microenvironment." (PMID 41427020, 2025). "The cytokine profile observed in this study, characterized by reduced IL-6 and IL-8 levels with increased TNF-α secretion, suggests that HYP-PDT shifts the tumor microenvironment from a STAT3-dependent pro-tumor state toward an NF-κB–driven pro-inflammatory response." (PMID 41226910, 2025). "B lymphocytes act via interferon-gamma and tumor necrosis factor-alpha to control cancer progression, while natural killer cells participate in tumor defense by attacking cancer cells without antigen activation." (PMID 40016853, 2025). "Among the main cytokines involved in tumor immunity are IFN-γ, TGF-β, TNF-α, IL-10, and IL-17." (PMID 39860614, 2025). "Inflammatory cytokines, such as tumor necrosis factor-α (TNF-α), interleukin-6 (IL-6), and interleukin-8 (IL-8), as well as platelet agonists like thrombin and ADP, present in the tumor microenvironment, promote platelet autophagy, resulting in platelet activation." (PMID 39852571, 2025). "Furthermore, response patients demonstrated enhanced signaling in immune-regulating pathways, such as TNF and CXCL, indicating that CD52 + DCs play a key role in modulating immune responses and shaping the tumor microenvironment." (PMID 40971094, 2025). "These tumours displayed increased infiltration of natural killer (NK) and γδ T cells, in addition to increased expression of various cytokines consistent with a type 1 immune response including IFN-γ, IL-12 and TNF-α." (PMID 40057603, 2025). "Particularly, M1-type TAMs secrete a repertoire of pro-inflammatory cytokines including IL-1β, IL-6, and tumor necrosis factor-alpha (TNF-α), alongside generating ROS that potentially inflict DNA damage, thus catalyzing innate immune responses conducive to the obliteration of tumor cells." (PMID 40664640, 2025). "To investigate whether the secretory capacity for other cytokines differed between TNF-α High and TNF-α Low tumor types, we compared the secreted levels while controlling for age, sex, and tumor size using a generalized least squares (GLS) model." (PMID 39923035, 2025). "Additionally, γδT cells also produce TNF-α, which binds to TNF receptors on tumor cells, further promoting apoptosis via extrinsic signaling cascades." (PMID 40226616, 2025). "M1 TAMs, typically induced by microbial products or Th1 cytokines (e.g., IFN-γ), secrete pro-inflammatory cytokines (TNF-α, IL-12, IL-1β), generate reactive oxygen and nitrogen species (ROS/RNS), and promote antigen presentation, thereby stimulating anti-tumor immune responses." (PMID 40746533, 2025).
tumor (continued). "Having observed Bevacizumab promotion of TNF-α induction of expression of ICAM-1 and VCAM-1 on the surface of HUVECs above, next we looked at the signs of effective priming of T cells to cross the blood vessel wall into the tumour microenvironment." (PMID 40650058, 2025). "Simultaneously, compared with the control group, the combination treatment group exhibited a significantly higher frequency of TNF-α+ IFN-γ+ CD8+ T cells in the dLNs, as well as increased proportion and absolute number of IFN-γ+ and GZMB+ CD8+ T cells in tumor-infiltrating lymphocytes." (PMID 40290124, 2025). "Necrotic areas of the tumor may release factors that facilitate tumor growth and metastasis, such as vascular endothelial growth factor (VEGF) and tumor necrosis factor‐alpha (TNF‐α)." (PMID 41017311, 2025). "APOL1, TNF, and VIM co-expressed in myeloid cells, indicating that PANoptosis–lactylation interplay may counteract APOL1’s tumor-promoting effects by activating caspase cascades." (PMID 40649778, 2025). "mRNA expression of CXCL9, iNOS, and IL-12β, anti-tumor macrophage markers, was elevated, while mRNA expression of IFNγ, TNFα, ARG-1, TGFβ, IL-10, and VEGFa, pro-tumor macrophage markers, was significantly lower in TAMs isolated from the prostates of RON∆Epi/TRAMP+ compared to RONF/F/TRAMP+ mice." (PMID 40282397, 2025). "LOX enhances the hypoxia adaptation of tumour cells by upregulating HIF‐1α, which in turn activates the NF‐κB pathway and drives the secretion of inflammatory factors (e.g., IL‐6, TNF‐α), further recruiting immunosuppressive cells (e.g., TAMs, MDSCs) to form a pro‐cancer TME." (PMID 40179101, 2025). "Furthermore, H-151 not only inhibited the p-STING/p-IRF3 axis but also significantly reduced the expression of T cell infiltration and activation markers (CD3D and CD69) as well as anti-tumor factors (GZMB, IFNγ, and TNFα)." (PMID 40846839, 2025). "Furthermore, Amuc_C triggered IL-1β, TNF-α, and IFN-γ productions, significantly decreasing tumor growth, and prolonged overall survival." (PMID 41170411, 2025). "Interaction with host immune cells further accelerates tumor-promoting inflammation: E. coli engages the TLR4/NF-κB signaling axis to induce pro-inflammatory cytokines, including IL-6, IL-8, and TNF-α, which sustain tumor-promoting microenvironments and facilitate angiogenesis." (PMID 41356485, 2025). "Their natural tumor-tropism is a crucial feature of MSCs as drug delivery carriers, with tumor tissues secreting cytokines (like TNF-α, IL-6, and SDF-1) that activate MSC-related signaling pathways (such as PI3K/Akt, MAPK, JAK/STAT), inducing their migration to the tumor microenvironment." (PMID 40142943, 2025). "In addition, increased expression levels of TNF, IL-12 and IFN-γ were observed in tumor tissues treated with H101 or PD-1 blockade." (PMID 40296909, 2025). "Additionally, high levels of TNF-α correlated with more advanced tumor stages in CRC patients, while the overexpression of iNOS is known to promote tumor angiogenesis and metastasis." (PMID 41011849, 2025). "Furthermore, the expression levels of TNF-α, IL-6, IL-1β, and NOS2 in tumor tissues were enhanced following CIRT treatment compared to the control group (p < 0.001)." (PMID 40917841, 2025). "Compared to the control groups, TNF-α levels in tumor tissues were not significantly elevated after PF/GEM@mPLV treatment." (PMID 40700478, 2025). "This immune reprogramming can be mediated through sustained exposure to tumor-derived cytokines such as IL6 (interleukin-6), TNFα (tumor necrosis factor-alpha), IL1β (interleukin-1 beta), TGFB (transforming growth factor beta), chemokines, growth factors, and extracellular vesicles." (PMID 41514627, 2025). "Moreover, the newly induced SASP characteristics by IFI30 knockdown, including elevated levels of IL‐6, IL‐8, and TNF‐α, as well as decreased levels of TGF‐β and MMP‐9, reflect the dynamic interplay between senescence and tumor suppression." (PMID 40186402, 2025).
tumor (continued). "Pro-inflammatory cytokines such as interleukin-1 beta (IL-1β), interleukin-6 (IL-6), and tumor necrosis factor-alpha (TNF-α)—primarily secreted by macrophages and other immune cells in the TME—are instrumental in both tumor progression, systemic immune modulation, and renal function." (PMID 41301732, 2025). "Elevated levels of TNF-α resulting from depressive states effectively activate multiple MAPK signaling pathways—including c-Jun N-terminal Kinase (JNK), ERK, and p38—thereby facilitating tumor progression." (PMID 41000397, 2025). "The T cell-mediated tumor cell killing assay showed that compared with 231M3PDL1, the apoptosis rate of 231M3N219Q was significantly inhibited, accompanied by the decrease of effector cytokines IFN-γ and TNF-α secreted by CD8+ T cells in co-culture system." (PMID 40760673, 2025). "SCs can be activated by tumour-secreted proteins, e.g., TNFα, which is characterized by the upregulation of activation markers (e.g., c-Jun, glial fibrillary acidic protein, and p75NTR) and the cascade expression of NGF and TNFα." (PMID 40783715, 2025). "Furthermore, TNF-α can potentially contribute to the re-regulation of immunosuppressive cells within the TME, including Tregs, thereby reducing the mechanisms of tumor immune evasion." (PMID 38778609, 2025). "Furthermore, increased levels of cytotoxic granules (Granzyme B and Perforin), anti-tumor cytokines (IFN-γ and TNFα), and the apoptotic marker CHOP/GADD153 were observed in MerTK-overexpressing tumors in both ICI treatment groups by IHC." (PMID 40391157, 2025). "Once activated, NK cells exert tumor-suppressive effects through perforin-granzyme-mediated apoptosis, death receptor pathways, and secretion of pro-inflammatory cytokines such as interferon-gamma (IFN-γ) and tumor necrosis factor-alpha (TNF-α)." (PMID 40917849, 2025). "Furthermore, tumor cells actively shape the immune microenvironment by secreting immunomodulatory cytokines such as CCL2, M-CSF, TNF, IL-10, and TGF-β, thereby amplifying the recruitment and M2 polarization of TAMs." (PMID 41459539, 2025). "The down-regulation of immune-checkpoint receptors (PD1, CTLA4, TIGIT, etc.), up-regulation of cytokines (IFN-γ, TNF-α, IL2), and activation of granzyme and perforin, etc., remained the primary readouts to characterize the antitumor potential of tumor-infiltrated and activated T-cells." (PMID 40593750, 2025). "The secretion level of TNF-α and IFN-γ in serum and tumor were detected." (PMID 40176815, 2025). "First, we conducted cocultures between expanded/unexpanded T cell pools and HLA-matched tumor cell lines (TCLs) for 10 hours, followed by measurement of intracellularly captured cytokines, IFN-γ, and TNF-α, and cytolytic degranulation through the marker CD107a in the CD8+ T cells." (PMID 38618958, 2024). "Chitin and anti-PD-1 combination treatment also increased IFN-γ levels—albeit not significantly—in 66cl4 primary tumor lysates and significantly increased TNF-α levels in both the 4T1 and 66cl4 primary tumors." (PMID 38605414, 2024). "Moreover, it has been reported that the tumor-infiltrating γδT17 subset mediating pro-angiogenic IL-17 thereby inducing the expression of VEGF-A, CXCL8, GM-CSF, and TNFα release, can actively participate in the angiogenic process and the recruitment of MDSCs." (PMID 38726320, 2024). "Derived TGF-β from tumor-infiltrating monocytes or macrophages might impair the expression of IFN-γ, TNF-α, and Ki-67 in NK cells." (PMID 39415291, 2024). "TDSFs, such as the vascular endothelial growth factor (VEGF), tumor necrosis factor alpha (TNF-α), transforming growth factor-β (TGF-β), and interleukins (ILs), such as IL-6 and IL-10, can derive from tumor cells, which are themselves induced by the local inflammatory microenvironment." (PMID 38391950, 2024). "We found that TNF-α and IL-1β could increase the expression of OPN in both tumor cells and macrophages, which might be the reason for the increased number of SPP1 + Macs." (PMID 39726047, 2024).